GLB1 (galactosidase beta 1)
Diseases named in the same sentence as GLB1 in open-access papers (continued):
Sharing a sentence is not in itself a finding about the gene and the disease.
GM1 gangliosidosis type 2 (4 papers, 2017 to 2025). GM1 gangliosidosis type 2 is a clinically variable, infancy or childhood-onset form of GM1 gangliosidosis characterized by normal early development and psychomotor regression between seven months and three years of age. "We have described a novel, pathogenic in‐frame deletion of GLB1 in a patient with GM1 gangliosidosis type II." (PMID 30187681, 2018). "A missense mutation in GLB1 gene, which segregated with the disease phenotype as autosomal recessive form of juvenile GM1 gangliosidosis type II was identified in four patients from the southwest of Iran." (PMID 28716012, 2017). "The identified mutation in GLB1 gene seems to have complete correlation with GM1 gangliosidosis type II and 100% penetrance in homozygous individuals." (PMID 28716012, 2017). "For instance, the GLB1 knockout mouse model, which recapitulates the natural history of type II GM1 gangliosidosis, has proven valuable for exploring potential therapeutic strategies." (PMID 40362326, 2025). "MD-020 (GLB1 p.R59H/p.Y36C) suffers from a GM1-gangliosidosis type II, with an onset at age 3 with dysphemia." (PMID 36233161, 2022). "We present a 22‐month‐old proband with GM1 gangliosidosis type II (late‐infantile form) in whom a novel homozygous in‐frame deletion (c.1468_1470delAAC, p.Asn490del) in GLB1 was detected." (PMID 30187681, 2018).
asthma (3 papers, 2015 to 2023). "It was hypothesized that the identified downregulation of M6PR, TPP1, GLB1, NEU1, ACP2, LAMP1 and HGSNAT leads to disorders of lysosome function, which results in asthma by causing T-cell dysfunction." (PMID 25633562, 2015). "These signals suggest a spectrum of shared genetic influences, some predominantly influencing asthma (FAM105A, GLB1, PHB, TSLP), others predominantly influencing fixed airflow obstruction (IL17RD, C5orf56, HLA-DQB1)." (PMID 35104449, 2022). "Four of the eight signals identified as novel (GLB1, FAM105A, PHB, TSLP) are known signals for asthma or allergic disease, but not COPD." (PMID 35104449, 2022).
Ataxia (3 papers, 2017 to 2025). Ataxia refers to impaired coordination of voluntary muscle movement. "Our results confirm a link between GLB1 gene mutation, ataxia and neurodegeneration in patients with juvenile gangliosiodis type II in Iran." (PMID 28716012, 2017). "Therefore, GLB1 genetic test should be requested for individuals with childhood ataxia and family members of known patients who intend to have consanguineous marriage." (PMID 28716012, 2017). "With the exception of SLC6A3 and PLA2G6, which primarily manifest with dystonia and parkinsonism as key features, we found that GLB1, SLC30A10, and SLC39A14 predominantly exhibit a dystonic phenotype, sometimes accompanied by other movement disorders, such as parkinsonism or ataxia." (PMID 40362326, 2025).
cardiomyopathy (3 papers, 2010 to 2023). A disease of the heart muscle or myocardium proper. "The mutations identified in patient 2 with cardiomyopathy were localized in the GLB1 gene region common to both lysosomal beta-galactosidase and elastin binding protein (EBP), and caused a deletion in the elastin-binding domain of EBP." (PMID 20920281, 2010). "Patients with GLB1‐related MBD exhibited the following visceral manifestations: Corneal clouding (P4, P5, P16), cardiac valve pathology (P12, P16), cardiomyopathy (P16), and hepatosplenomegaly (P11)." (PMID 34258138, 2021).
diabetes (3 papers, 2020 to 2023). "Elevated levels of GLB1, a lysosomal marker of cell senescence, is associated with increased liver fat, NAFLD, aging, and type 2 diabetes mellitus, and the low levels of GLB1 seen in our study is in contrast to our other markers pointing at accelerated aging." (PMID 38250971, 2023). "Muscle aging (Atrogin 1 and Glb1), diabetes (RAGE and CD163), and intracellular lipid accumulation (CD36 and PPARγ) related mRNA and protein expressions and FMOD were analyzed in MSTN knockout gas muscles." (PMID 34440852, 2021). "Muscle aging is associated with diabetes and obesity, and in the present study, we compared the expressions of the FMOD and MSTN genes and those of genes related to muscle aging (Atrogin 1, Glb1), diabetes (RAGE, CD163) and intracellular lipid accumulation (CD36, PPARγ) in vivo and in vitro." (PMID 34440852, 2021).
dysostosis multiplex (3 papers, 2020 to 2021). "The aim of this study was to describe the clinical and genetic findings in a cohort of patients living and diagnosed in Brazil, South America's largest country presenting with GLB1 deficiency and dysostosis multiplex." (PMID 34258138, 2021). "We describe 17 individuals diagnosed with GLB1 deficiency presenting with various degrees and combinations of dysostosis multiplex and neurologic/neurocognitive dysfunction." (PMID 34258138, 2021). "We investigated 17 patients with GLB1‐related dysostosis multiplex, 14 of whom were categorized as GLB1‐related MBD, and 3 as GLB1‐related mild dysostosis without distinct features of MBD." (PMID 34258138, 2021). "Morquio‐B disease (MBD) is a distinct GLB1‐related dysostosis multiplex involving the trabecular parts of long bones and spine, presenting a mild phenocopy of GALNS‐related Morquio‐A disease." (PMID 32071837, 2020).
Dystonia (3 papers, 2022 to 2026). An abnormally increased muscular tone that causes fixed abnormal postures. "In another study of 16 patients aged 3–30 years, dystonia, parkinsonian features, and facial grimacing were correlated with underlying GLB1 variants." (PMID 41500845, 2026). "A study employing whole‐exome sequencing (WES) in four children presenting around age 3 years identified rare pathogenic GLB1 missense variants associated with ataxia, dystonia, and global developmental regression." (PMID 41500845, 2026). "This systematic review explores the genotype–phenotype correlations of GLB1, SLC6A3, SLC30A10, PLA2G6, and SLC39A14—recently classified as DYT SLC39A14 and historically linked to dystonia-parkinsonism." (PMID 40362326, 2025). "Of those, five patients presented MDs such as dystonia or parkinsonism, spasticity, and suspicion of brain iron deposits or GP hypointensities; they were associated with variants in FBXO7, FUCA1, GLB1, TPP1, and KIF1A." (PMID 36233161, 2022). "Our analysis showed dystonia-parkinsonism predominates in SLC6A3 and PLA2G6, while GLB1, SLC30A10, and SLC39A1 show predominantly dystonic phenotypes with a low frequency of parkinsonism." (PMID 40362326, 2025). "However, we observed that the proportion of individuals manifesting parkinsonism in GLB1, SLC30A10, and SLC39A14 is lower than expected under the DYT/PARK nomenclature, where dystonia and parkinsonism should generally coexist or be prominent features in approximately half or more of the patients." (PMID 40362326, 2025).
galactosialidosis (3 papers, 2013 to 2025). A lysosomal storage disease characterized by coarse facial features, macular ''cherry red spot'', and dysostosis multiplex. "In contrast, in MPS IIIC mouse brains, NEU1 was deficient but GLB1 was increased, and GALNS was only slightly reduced, as in the tissues of galactosialidosis CathAS190A-neo mice, consistent with high stability of mouse GLB1 and GALNS enzymes in the lysosome." (PMID 40540388, 2025). "The gel-filtration profiles of NEU1 and GLB1 activities were compared for the WT, HgsnatP304L, and galactosialidosis CathAS190A-Neo mice." (PMID 40540388, 2025).
Mucopolysaccharidoses (3 papers, 2022 to 2024). "Beyond sphingolipid/ceramide metabolism, our screen also identifies many fly homologs of genes causing human mucopolysaccharidoses (e.g., GLB1, IDS, IDUA, MAN2B1, MANBA)." (PMID 37200393, 2023). "In an independent longitudinal proteomics dataset we replicated αSyn-induced increases among 6 of these proteins, including Npc1a and several proteins homologous to human LSD gene products causing mucopolysaccharidoses: GLB1/Ect3, MAN2B1/LManII, and MANBA/Beta-Man." (PMID 37200393, 2023).
Obesity (3 papers, 2017 to 2025). Accumulation of substantial excess body fat. "When adjusting for both sex and chronological age, we observed that GLB1 and ZMAT3 expression remained significantly elevated in the subjects with obesity (Sup." (PMID 40127780, 2025). "Adjusting for sex alone did not alter the significant upregulation of GLB1, ZMAT3, CDKN1A, and CDKN2A in individuals with obesity (Sup." (PMID 40127780, 2025).
Parkinsonism (3 papers, 2022 to 2025). Characteristic neurologic anomaly resulting from degeneration of dopamine-generating cells in the substantia nigra, a region of the midbrain, characterized clinically by shaking, rigidity, slowness of movement and difficulty with walking and gait. "Given the predominantly neurological presentation of these conditions, it is likely that missing data on cardinal signs/symptoms, such as parkinsonism in GLB1, SLC30A10, and SLC39A14, reflect their actual absence." (PMID 40362326, 2025). "This review on GLB1, SLC6A3, SLC30A10, SLC39A14, and PLA2G6 is the third MDSGene review series on DYT/PARK genes, following previous articles on DRD genes and X-linked dystonia-parkinsonism." (PMID 40362326, 2025). "The results showed that the expression levels of GLB1, ASAH1 and PSAP in the Parkinson’s disease (PD) group were significantly higher than those in the control group, which further supports our finding that these five small molecule RNA genes (SMRGs) may be biomarkers for Parkinson’s disease." (PMID 40534738, 2025).
type 2 diabetes (3 papers, 2018 to 2023).
Anxiety (2 papers, 2021 to 2025). Intense feelings of nervousness, tension, or panic often arise in response to interpersonal stresses. "Notably, 6.7% (3 genes) - Glb1, Pla2g7 and Shbg - of the investigated amygdala genes showed significant correlations with both anxiety measures and mPFC gene expression." (PMID 41173860, 2025).
colorectal cancer (2 papers, 2021 to 2025). A primary or metastatic malignant neoplasm that affects the colon or rectum. "qPCR analyses confirmed the expression of 67EBP in colorectal cancer cells and its absence in normal intestinal crypt cells, although GLB1, from which the 67EBP is derived by alternative splicing, was detected." (PMID 40141206, 2025).
depression (2 papers, 2021 to 2024). "For example, a GWAS of major depressive disorder stratified by sex in two large biobanks, Generation Scotland and UK Biobank, found that the genes CRTAP, GLB1, and TMPPE at chromosome 3p22.3 were significantly associated with major depressive disorder in males, but not in females." (PMID 38790194, 2024).
GM1 gangliosidosis type 1 (2 papers, 2023 to 2025). GM1 gangliosidosis type 1 is the severe infantile form of GM1 gangliosidosis with variable neurological and systemic manifestations. "Homozygous or compound heterozygous mutations of the gene encoding for beta-galactosidase-1 (GLB1) on chromosome 3p22.3 can originate two clinically distinct, albeit allelic, disorders: GM1-gangliosidosis type 1 and mucopolysacharidosis type IVB, also known by the eponym Morquio syndrome type B." (PMID 37239976, 2023). "Clinical exome sequencing analysis identified two heterozygous pathogenic variants in GLB1: c.245 + 1 G > A (p.?; ClinVar accession VCV000417873.6) and c.202C > T (p.Arg68Trp; ClinVar accession VCV000000944.7), confirming the diagnosis of autosomal recessive GLB1-related GM1 gangliosidosis type 1." (PMID 39897471, 2025).
Lysosomal disease (2 papers, 2022 to 2025). "GLB1-related disorders are autosomal recessive lysosomal diseases caused by enzymatic deficiency of β-galactosidase." (PMID 39897471, 2025).
metastatic disease (2 papers, 2015 to 2017). "Within primary tumors, elevated GLB1 associates with lower T stage (p=0.01), localized versus metastatic disease (p=0.0003) and improved PSA-free survival (p=0.03)." (PMID 25876105, 2015). "Localized cancer appears more similar to HGPIN, demonstrating less heterogeneity and increased numbers of GLB1 positive, senescent-like cells than primary tumors that have given rise to metastatic disease." (PMID 25876105, 2015).
Type 1 diabetes (2 papers, 2018 to 2020). "Interestingly, all enzymes involved in keratan sulfate degradation (ie., GALNS, GLB1, GNS, HEXA, and HEXB) were elevated in urines from youths with type 1 diabetes, compared to non-diabetic youths." (PMID 32453760, 2020).
atopic asthma (1 paper, 2015). An asthma that is characterized by symptoms that are triggered by an allergic reaction caused by inhaled allergens such as dust mite allergen, pet dander, pollen and mold. "Among the genes identified in the present study (M6PR, TPP1, GLB1, NEU1, ACP2, LAMP1 and HGSNAT) that were significantly associated with lysosomal function, only TPP1 has been confirmed as being associated with atopic asthma." (PMID 25633562, 2015).
benign prostatic hyperplasia (1 paper, 2015). A non-cancerous nodular enlargement of the prostate gland. "Benign prostatic hyperplasia (BPH) also increased GLB1 expression compared to benign peripheral prostate tissues consistent with increased SA-β-gal activity seen previously in these tissues." (PMID 25876105, 2015).
cardiac hypertrophy (1 paper, 2022). "Here the authors generate a Glb1+/m‒Glb1-2A-mCherry (GAC) reporter mouse model, where the GAC signal is consistently correlated with established biomarkers of cellular senescence, cardiac hypertrophy and shortened lifespan, which may prove helpful for studies developing anti-aging interventions." (PMID 36396643, 2022).
diabetic nephropathy (1 paper, 2020). "Two lysosomal enzymes, ARSA and GLB1, were highlighted as part of the predictive profile for diabetic nephropathy." (PMID 32453760, 2020).
dysplasia (1 paper, 2022). A usually neoplastic transformation of the cell, associated with altered architectural tissue patterns. "GLB1‐related disorders compromise two phenotypes, GM1 and Morquio B. MRI findings such as hyperintensity of the putamen or general atrophy would have supported a GM1 phenotype, and spondyloepyseal dysplasia on the contrary would have supported a Morquio B phenotype." (PMID 36341176, 2022).
hepatocellular carcinoma (1 paper, 2016). A malignant tumor that arises from hepatocytes. "The GLB1 rs4678680 single nucleotide polymorphism (SNP) has been identified as a hepatocellular carcinoma (HCC) susceptibility polymorphism by a genome-wide association study in Korean population previously." (PMID 27489354, 2016).
Hip dysplasia (1 paper, 2021). The presence of developmental dysplasia of the hip. "Among the 14 patients with GLB1‐related MBD, the most frequently observed skeletal manifestations were located in the hips and in the spine, with spinal vertebral dysplasia in 12 of the 14, hip dysplasia in 11 of the 14 patients, and scoliosis/ kyphosis/ gibbous in 7 of the 14 patients." (PMID 34258138, 2021).
hyperphosphatemia (1 paper, 2026). Abnormally high level of phosphate in the blood. "Genetic testing for GLB1 should be considered in cases of persistent hyperphosphatemia, especially if it is associated with any other clinical indicator of GM1, such as limb edema." (PMID 41800148, 2026).
lipid metabolism disorders (1 paper, 2025). "This study identifies FADS1, FADS2, GLB1, and PNPLA3 as key genes integrating both lipid metabolism disorders and inflammation in MAFLD, with potential diagnostic implications." (PMID 41007773, 2025).
lung carcinoma (1 paper, 2015). "Of these 64 mRNAs, 38 mRNAs were down-regulated in lung cancer patients, of which the top 5 mRNAs were CHGB, B4GALT1, ZNF434, GLB1, and ASCL1 (p≤0.0001)." (PMID 25705890, 2015).
lymphoma (1 paper, 2023). A malignant (clonal) proliferation of B- lymphocytes or T- lymphocytes which involves the lymph nodes, bone marrow and/or extranodal sites.
mental retardation (1 paper, 2012). "IM4 is the second most upregulated gene in parkin mutants, IM10 is upregulated in flies with neurodegeneration caused by mutated human tau, and Ect3 is the homolog of GLB1, a human gene associated with mental retardation." (PMID 22978642, 2012).
oculogyric crisis (1 paper, 2025). A focal dystonia that is characterized by a prolonged involuntary upward deviation of the eyes. "While certain features like seizures or oculogyric crisis may be found in GLB1 and PTS, or SLC6A3 and SPR, respectively, levodopa response is more inconsistent in GLB1, SLC6A3, SLC30A10, and SLC39A14, and should guide the diagnosis." (PMID 40362326, 2025).
osteosarcoma (1 paper, 2022). A usually aggressive malignant bone-forming mesenchymal neoplasm, predominantly affecting adolescents and young adults. "Moreover, we found that overexpression of GLB1 inhibits the invasion of human osteosarcoma cell lines from the results of transwell assay." (PMID 36313783, 2022). "We revealed that overexpression of GLB1 could inhibits the migration of human osteosarcoma cells." (PMID 36313783, 2022).
ovarian carcinoma (1 paper, 2014). A malignant neoplasm originating from the surface ovarian epithelium. "One branch clustered eight genes (NAGA, B4GALT6, HEXA, GLB1, GBA, GLA, UGCG, HEXB) with generally comparable expression levels among the cell lines, except for the UGCG gene which was expressed at considerably higher levels in both HOSE cell lines compared with the ovarian cancer cell lines." (PMID 25294702, 2014).
Pick disease (1 paper, 2017). A rare neurodegenerative disorder leading to dementia. "The gene Niemann-Pick disease, type C2 (NPC2) is upregulated in early disease and is connected to cathepsins L and B (CTSL, CTSB) and GLB1 in the lung network." (PMID 28330499, 2017).
prostatic intraepithelial neoplasia (1 paper, 2015). "In tissue arrays, quantitative imaging detects increased GLB1 expression in high-grade prostatic intraepithelial neoplasia (HGPIN), known to contain senescent cells, and cancer compared to benign prostate tissues (p<0.01) and senescent cells contain low Ki67 and elevated HP1γ." (PMID 25876105, 2015).